IL6 (interleukin 6)
Diseases named in the same sentence as IL6 in open-access papers (continued):
Sharing a sentence is not in itself a finding about the gene and the disease.
renal cell carcinoma (80 papers, 1998 to 2025). "For example, in renal cell carcinoma, elevated IL-6 levels are linked to metastasis, while in breast cancer, distinct cytokine signatures have been shown to discriminate between tumor subtypes and predict metastatic potential." (PMID 40362613, 2025). "G3BP1 also causes tumor progression and metastasis in renal cell carcinoma cells by over-expression along the IL6 / G3BP1 / STAT3 pathway." (PMID 34604242, 2021). "It was found that plasma levels of SRLR (sorafenib resistance-associated lncRNA in renal cell carcinoma) and IL-6 in PCOS patients were positively correlated and higher in comparison to healthy controls." (PMID 33920227, 2021). "Increased IL-6 is known to be associated with invasiveness, metastasis, and prognosis of renal cell carcinoma." (PMID 31466366, 2019). "Similarly, it has been recently reported that high IL6 levels are associated with poorer outcomes and lower treatment response in renal cell carcinoma patients." (PMID 37120444, 2023). "In particular, interleukin-6 is involved in fever associated with renal cell carcinoma." (PMID 35905253, 2022). "A recent study showed that ISG15 can promote proliferation and metastasis through IL6/JAK2/STAT3 signaling in renal cell carcinoma." (PMID 40874680, 2025). "that high serum IL-6 correlated with dysfunctional CD8+ T cells in patients with renal cell carcinoma and that inhibition of IL-6 signaling alleviated the break on effector cell differentiation in tumor-bearing mice." (PMID 39128004, 2024). "Recent studies have also reached consistent conclusions, such as elevated IL-6 levels, suggesting a poor response to pembrolizumab therapy in advanced renal cell carcinoma treatment, as well as worse survival outcomes." (PMID 38903721, 2024). "ApoE-/- upregulated IL-6, Renal cell carcinoma, PRRs in recognition of bacteria and viruses, VDR/RXR activation, Phenylalanine degradation IV pathways in Ly6Chigh MC." (PMID 34987524, 2021). "Evidence shows that G3BP1 promotes tumour progression and metastasis through the IL-6/G3BP1/STAT3 signalling axis in renal cell carcinoma." (PMID 33579337, 2021). "For example in renal cell carcinoma, a high IL-6 correlates to cancer metastasis, while high IL-6 and IL-17 measurements predict cancer recurrence following radical treatment." (PMID 34307156, 2021). "For example, hypoxia-induced IL-6 and IL-8 promote renal cell carcinoma cell invasion, which is dependent on NOX4 expression." (PMID 32641980, 2020). "As a previous study indicates that NOX4 mediates hypoxia-induced IL-6 production in renal cell carcinoma cells, we next sought to the possible correlation of NOX4 and IL-6 expression levels in NSCLC." (PMID 25504436, 2015). "A previous study indicates that NOX4 mediates production of various pro-inflammatory cytokines including IL-6 in renal cell carcinoma cells." (PMID 25504436, 2015). "In particular, metastatic renal cell carcinoma (RCC) is frequently associated with elevated levels of IL-6, which have been reported to correlate with metastatic progression, poor prognosis, shorter survival, as well as poor response and high toxicity to IL-2 therapy." (PMID 20808314, 2010). "Serum interleukin (IL)-6 levels correlate with disease outcomes in renal cell carcinoma (RCC) patients." (PMID 20808314, 2010). "In order to elucidate the relation between renal cell carcinoma and the host, serum levels of inflammatory cytokines, interleukin-6, tumour necrosis factor α, interleukin-1β, were measured." (PMID 11986770, 2002). "Among these cytokines, interleukin-6 (IL-6) has been frequently studied in renal cell carcinoma (RCC)." (PMID 11986770, 2002). "Thirty years ago, a mouse monoclonal anti-IL-6 Ab was used to treat hematological cancers and renal cell carcinoma with significant activity on inflammatory symptoms and occasional antitumor activity, but limited duration of activity with the development of anti-mouse Ab." (PMID 39754984, 2025).
renal cell carcinoma (continued). "As the most common subtype of renal cell carcinoma, increased activity of NF-κB in KIRC has been shown to be associated with upregulation of angiogenic markers, and knockout of NF-κB leads to downregulation of IL-6." (PMID 37847185, 2023). "The expression of TIMP1 in renal cell carcinoma regulates the IL6-JAK-STAT3 pathway." (PMID 32420905, 2020). "PAK-1 mediated stem-like phenotype through NF-kB/IL6 activation in renal cell carcinoma." (PMID 31658701, 2019). "NOX may be linked to inflammation-induced metastasis in renal cell carcinoma (RCC), where cell invasion is based on NOX4-mediated hypoxic-induced production of interleukin-6 and interleukin-8 (IL-6 and IL-8)." (PMID 28626501, 2017). "Besides, NOX4 is also involved in renal cell carcinoma cell invasion and metastasis through hypoxia-induced interleukin 6- and 8- production." (PMID 24946933, 2014). "Renal cell carcinoma is known to produce excessive levels of IL-6 compared to other tumors." (PMID 25120953, 2014). "Besides, NOX4 has been also shown to promote renal cell carcinoma cell invasion through hypoxia-induced interleukin 6-and 8-production." (PMID 24946933, 2014). "In renal cell carcinoma, increased IL-6 production has been shown to correlate with expression of tumor suppressor gene proteins, and may be involved in the persistent activation of STAT transcription factors." (PMID 22870317, 2012). "IL-6 has been shown to be involved in the physiopathology of paraneoplastic inflammatory syndromes observed in patients with renal-cell carcinoma; a similar phenomenon might occur in metastatic breast cancer patients." (PMID 12771987, 2003). "In conclusion, interleukin-6 may be one of the factors for the poor prognosis of patients with renal cell carcinoma." (PMID 11986770, 2002). "Studies have shown that IL-6 can significantly increase proliferation and metastasis in cancers, such as renal cell carcinoma (RCC) due to the activation of JAK2/STAT3, a pro-inflammatory pathway." (PMID 39478996, 2024). "The levels of G3BP1, which plays a critical role in stress granule (SG) formation, are increased in renal cell carcinoma (RCC) and promote IL6/STAT3 activation." (PMID 31952344, 2020). "Furthermore, NOX4 is shown to increase IL-6 and IL-8 production in renal cell carcinoma." (PMID 28099519, 2017). "Sunitinib, a drug for the treatment of renal cell carcinoma, activates the NF-κB signaling pathway through the IRE1α/TRAF2/IKKβ axis of the ER stress response, enhancing the expression of IL-6, IL-8, and TNF-α." (PMID 38775480, 2024). "IL-6 has previously been shown to be the second most altered gene in HS5 cells as compared to HS27a and has been found to drive G6PD expression in renal cell carcinoma." (PMID 35213227, 2022). "Likely for the same reason, our results show that ZC3H12A is not the negative regulation of the proinflammatory cytokines (i.e., IL6, IL8) in CRC, different from what was reported in renal cell carcinoma." (PMID 31106233, 2019). "There is some evidence of IL6 and IL8 as prognostic biomarkers of survival in CRC patients and as predictive markers for response to bevacizumab treatment in renal cell carcinoma." (PMID 29535825, 2018). "Studies on renal cell carcinoma (RCC) cell lines (NC65, ACHN, CAKI-1, CCF-RC1) indicate that dexamethasone can inhibit cell proliferation in a dose-dependent manner, through the suppression of interleukin-6 (IL-6) gene expression." (PMID 40143180, 2025). "In renal cell carcinoma (RCC), EVs carrying circRNA circEHD2—found to be upregulated in tumor tissues—contribute to metastasis by inducing the secretion of the proinflammatory cytokine IL-6." (PMID 40867639, 2025). "There is indeed evidence that IL-6 acts as an intracrine growth factor in a variety of renal cell carcinoma cell lines which express no surface IL-6 receptors." (PMID 37143657, 2023). "However, IL6-specific antibody siltuximab demonstrated no efficiency against renal cell carcinoma and prostate cancer." (PMID 37006265, 2023).
renal cell carcinoma (continued). "G3BP1 contributes to the proliferation, migration and invasion of renal cell carcinoma (RCC), and knockdown of G3BP1 blocks the IL-6/STAT3 signaling and reduces the metastatic ability of RCC." (PMID 34526993, 2021).
renal failure (79 papers, 2009 to 2025). "The animals in the LPS+GM-CSF group showed a significant weight loss, mildly increased markers of liver and kidney failure and rhabdomyolysis and an increased release of IL-6 and IL-8." (PMID 31220157, 2019). "These metabolites significantly inhibit the expression and release of inflammatory cytokines (e.g., TNF-α, IL-1β, and IL-6) induced by podocyte injury, which helps improve renal insufficiency caused by podocyte dysfunction and prevents renal parenchymal damage." (PMID 41194878, 2025). "Safety and tolerability of distinct IL-6 signaling inhibitors in RA patients with renal insufficiency have been generally established." (PMID 39723211, 2024). "Relevant literature have shown that IL6, AKT1, VEGFA, FN1, TIMP1, ALB and TNF are associated with renal insufficiency." (PMID 36209090, 2022). "Patients with renal insufficiency, even in the early stage, have been reported to have high expression of inflammatory factors, such as hypersensitive C-reactive protein, interleukin-6 and fibrinogen." (PMID 34674646, 2021). "Serum IL-6 level of diabetic patients with kidney failure exhibited a significant increase when compared with that of patients with either DM or kidney failure." (PMID 33442388, 2020). "Our previous study confirmed that the level of TNF-α was increased in T2DM patients, and the current study showed levels of plasma TNF-α and IL-6 were elevated in T2DM patients with renal insufficiency and were inversely related to the eGFR." (PMID 31637265, 2019). "Effects of IL-6 signaling inhibitors in terminal renal insufficiency." (PMID 39723211, 2024). "It has been reported that an elevation of either C-reactive protein (CRP) or interleukin-6 (IL-6), as a biomarker of systemic inflammation, was strongly associated with CVD in peritoneal dialysis (PD) patients, as well as risk factors of both all-cause and cardiovascular mortality." (PMID 30445969, 2018). "There was a marginally significant correlation between serum IL-6 levels and TSAT in 34 peritoneal dialysis patients (r = 0.067, p = 0.078)." (PMID 24576354, 2014). "Both patients with CKD and AKI showed signs of inflammation such as higher leukocytes, procalcitonin and IL6 as compared to those without kidney failure." (PMID 33025516, 2021). "The observed inverse association between total fecal ODA and serum proinflammatory markers, such as CRP, IL-6, and MCP-1, suggests that gut microbiota’s ODA may exacerbate chronic inflammation, which is known to play a critical role in the progression of CVD in patients with kidney failure." (PMID 38138292, 2023). "Concomitant with these effects on serum TNF-α, IFN-γ, and IL-6 levels, HOMA-IR and HOMA-IS, the CRP (marker of inflammation) was most deleteriously affected in nephrotic diabetic patients without kidney failure." (PMID 33442388, 2020).
Granuloma (78 papers, 2006 to 2026). A compact, organized collection of mature mononuclear phagocytes, which may be but is not necessarily accompanied by accessory features such as necrosis. "Beyond its Th17-suppressive and skin-barrier-restorative activities, tapinarof directly dampens LL-37-induced mast-cell degranulation, down-regulating chymase-1, tryptase-β, MMP-9, TNF-α and IL-6—mediators implicated in granuloma formation." (PMID 41451029, 2026). "In-vitro data further show that tapinarof attenuates LL-37–driven mast-cell degranulation and decreases MMP-9, TNF-α, and IL-6, all implicated in granuloma formation and dermal remodeling." (PMID 41451029, 2026). "IL-6 and TNFα have been associated with the formation of granuloma and chronic wasting syndrome in paratuberculosis but their role is not yet clearly defined." (PMID 38399810, 2024). "Pro-inflammatory cytokines, especially TNF-α, IL-6, IL-1β, and IL-8, not only induce inflammation but also cause leukocyte infiltration, granuloma formation, and tissue fibrosis." (PMID 34681651, 2021). "Other than IFN-γ and TNF-α, the presence of IL-6 and IL-23 have been associated to formation and maturation of granulomas." (PMID 33312173, 2020). "Corroborating our previous findings, the Pb18-infected IL-6- and IL-17RA-deficient mice showed diminished capacity to mount organized granulomas at 30 dpi when compared to C57BL/6 group." (PMID 28871251, 2017). "Several pro-inflammatory cytokines such as tumor necrosis factor (TNF)-α, interferon (IFN)-γ, IL-6, IL-12 and IL-18 have been associated with granuloma formation on large vessels." (PMID 28400869, 2017). "To inhibit the development of Th17 cells during HP we used mice deficient in IL-6 and exposed them to S. rectivirgula for 3 weeks to measure the development of granulomas." (PMID 21699708, 2011). "IL-23A played a more important role than IL-6 for Th17 differentiation in leprosy which is reminiscent of the report on Mycobacterium bovis infection in a murine model where IL-17 was observed from day 1 of infection, was dependant on IL-23 and associated with granuloma formation." (PMID 23936569, 2013). "Compared to “healthy” lung parenchyma, the concentration of proinflammatory cytokines IL-6, IL-11, IL-17, and IFNγ, which are responsible for granuloma organization and infection focus delineation, was increased in the tuberculoma wall." (PMID 39519346, 2024). "Other than that, a Th17 response has also been associated with granuloma formation and fibrosis, whose activation is related to TGF-β and IL-6." (PMID 37373379, 2023). "Again, similar findings were confirmed by immunohistochemistry, which showed that the expression of IFN-γ, IL-10, TGF-β3, and IL-6 at the periphery of granulomas in KO rats were significantly lower than those in WT rats." (PMID 35584107, 2022). "Cytokines such as IL-1β, IL-4 IL-5, IL-6, IL-13, TNF-α, MCP-1, and TSLP induce allergy-related inflammation, which causes tissue fibrosis, granuloma formation, and leukocyte infiltration." (PMID 36235405, 2022). "At 3-months post- L-GSH supplementation, untreated (control) in vitro granulomas produced significantly less IL-6 in response to in vitro M. tb infection when compared to before to L-GSH supplementation." (PMID 34150674, 2021). "DEM treatment was also associated with an increase in IL-6, TNF-α and ill-formed granulomas in infected mice." (PMID 35371562, 2021). "Studies have shown that JAK-STAT signalling is constitutively activated in sarcoidosis, In sarcoidosis, dysregulated signalling of cytokines, such as IFN-γ and IL-6, which help to develop granuloma formation, occurs via the JAK-STAT pathway." (PMID 34781959, 2021). "The reduced acetyl-CoA level suppresses H3K9Ac-mediated expression of the host proinflammatory cytokine Il6, thus promoting granuloma progression." (PMID 34608123, 2021).
Granuloma (continued). "In reverse, inflammatory responses measured by IL-6 gene expression was higher in periapical abscess and granuloma than radicular cysts and healthy control." (PMID 34749700, 2021). "Patients of TS frequently presented more granuloma, caseous necrosis, epithelial-like reaction, interleukin 6 (IL-6), and C-reactive protein (CRP) than those of BS." (PMID 33959835, 2021). "Inflammatory mediators such as interleukin-1α (IL-1α), TNF-α and IL-6 are recognized to be involved in the formation of the granuloma." (PMID 30917586, 2019). "Using the ELISA technique, our results showed that the rats challenged with cotton pellet-induced granuloma had significantly elevated levels of the proinflammatory markers, IL-6 and TNF-α, as compared to normal control group (respectively)." (PMID 31263381, 2019). "L-GSH treatment of BCG granulomas resulted in a significant reduction in the levels of proinflammatory cytokines such as IL-6 and TNF-α, and a decrease in oxidative stress." (PMID 29494546, 2018). "The messenger RNAs of proinflammatory cytokines TNF-α, IL-1β, and IL-6, which initiate the fibrotic process, have been demonstrated in macrophages located at the periphery of granulomas." (PMID 30037796, 2018). "The production of IL-6, a proinflammatory cytokine released by macrophages and T cell in order to trigger inflammation, was reduced when the granulomas were treated with L-GSH among the healthy individuals." (PMID 29494546, 2018). "Comparison between the pro- and anti-inflammatory cytokines in granulomas revealed that IL-4 expression was significantly higher when compared with IL-6 (p=0.001) and TNF-α (p=0.001)." (PMID 29898177, 2018). "Increase IFNγ & TNF-α levels and PMN cells & functions.Increase T helper CD4 T cells & CD8 T cells activity.Improve Ag- specific antibody response.Restored DTH response and Granuloma formation.Reduced IL-6 cytokine and bacterial load." (PMID 30534129, 2018). "In contrast, most of the granulomas from IL-6−/− and IL-17RA−/− mice exhibited an intermediate size and immature profile with few lymphocytes forming the peripheral ring, associated with a diffuse inflammatory process." (PMID 28871251, 2017). "As granuloma formation and maintenance has been associated with the release of TNF-α and IL-6 in M. tuberculosis, we assessed the presence of these cytokines in the supernatants of infected macrophages." (PMID 27757105, 2016). "The different capacities of R and S morphotypes to kill macrophages and induce the formation of granulomas, and the secretion of IL-6 and TNF-α were determined." (PMID 27757105, 2016). "TNF-α and IL-6 are thought to play significant roles in S. japonicum egg induced granuloma formation." (PMID 25582427, 2015). "Another experimental study reported a high production of IL-6 by cultures of macrophages isolated from granulomas in response to SEA antigen." (PMID 24757288, 2014). "A diverse array of cytokines has been shown to influence the formulation and maintenance of Mtb granulomas, including TNFα and IL-6." (PMID 23577168, 2013). "The induction of IFNγ and IL-12 and the depletion of IL-4 producing NK cells has been attributed to TDM as well as a role, along with IL-6 and TNFα, in stable granuloma formation." (PMID 22738036, 2012). "The S. rectivirgula exposed IL-6-/- mice had similar levels of alveolitis and granuloma formation as well as an increase in IFNγ+ T cells compared to the WT mice." (PMID 21699708, 2011). "Enrichment analysis revealed upregulated immunological pathways related to granuloma formation in pulmonary sarcoidosis PBMCs, including T helper 17 and tumor necrosis factor-alpha signaling pathways, IL-1B, IL-6, and IL-17 production, and response to external stimuli." (PMID 41463010, 2025).